IL6 (interleukin 6)
Diseases named in the same sentence as IL6 in open-access papers (continued):
Sharing a sentence is not in itself a finding about the gene and the disease.
Sepsis (continued). "Additionally, sepsis induced higher expression of IL-6 and IL-10 by liver macrophages, with in vivo blocking of CD1d leading to reduction of IL-6 and augmentation of IL-10 systemic levels, further improving survival rates." (PMID 35163561, 2022). "TNFα, IL-6, IFNγ, IL-1β and IL-10 were measured in brain of mice 6 h after induction of sepsis." (PMID 33608025, 2021). "Indeed, our results show that therapeutical inhibition of active GzmA with serpinb6b similarly increased survival in WT and GzmK -/- mice and reduced IL-6 serum levels, confirming the potential of GzmA as a therapeutic target for sepsis treatment." (PMID 34815792, 2021). "The most severe and hyperinflammatory cases of sepsis-associated HLH could benefit from therapies that target cytokine storms, such as anakinra (anti-IL-1), tocilizumab (anti-IL-6), and/or ruxolitinib (anti-JAK2)." (PMID 34692727, 2021). "MYD88, NFKB1, and IL6 relative expressions were significantly higher in sepsis cases than controls." (PMID 34183713, 2021). "Finally, the concentration in serum of IL-6, a pro-inflammatory cytokine used as a marker of sepsis, was quantified." (PMID 33806791, 2021). "The inflammatory factors including TNF-α, IL-6 were increased significantly after sepsis, Mdivi-1 distinctly reduced the levels of TNF-α, IL-6 in serum, myocardial tissue, and vascular smooth muscle tissue, and the phosphorylation of NF-κ B p65 in myocardial tissue and vascular smooth muscle tissue." (PMID 34566637, 2021). "In addition, the concentration of plasma IL-10 correlated with the concentration of IL-6, suggesting that IL-10 is produced to regulate the inflammatory response typically mediated by IL-6 in sepsis." (PMID 35053151, 2021). "Therefore, the use of IL-6 signaling inhibition to treat sepsis should be very carefully considered." (PMID 34253862, 2021). "We hypothesized that IL-6 concentrations would be higher in MIS-C than sepsis, especially if shock was present." (PMID 34869111, 2021). "Interestingly, though, there was a strong positive correlation between sepsis scores and plasma concentrations of IL-6, IFNγ and TNFα." (PMID 34440538, 2021). "Moreover, blocking IL-6 has been suggested as a treatment strategy for inflammatory diseases such as sepsis." (PMID 34960054, 2021). "In an in vivo sepsis study, RvD1 decreased IL-6, TNFα, IL-1β and IFNγ levels significantly." (PMID 33815391, 2021). "In contrast, abundant data exist regarding the utility of IL-6 and IL-8 predicting sepsis outcomes." (PMID 32034914, 2021). "Next, we found that Pellino1 protein could induced the protein expression of Pellino1, TRAF6 and NF-κB and increased the levels of TNF-α, IL-6, IL-1β and IL-18 in mice of sepsis." (PMID 33632252, 2021). "dPGS or its analogs could be used in the therapeutic intervention in sepsis and inflammatory disorders to reduce unbound IL-6 in the plasma or tissues and its binding to the receptors." (PMID 33670858, 2021). "The excess or continuous production of IL-6—as seen in lethal sepsis—can be harmful." (PMID 35095877, 2021). "Levels of the IL-6 positively correlate with mortality in experimental models of sepsis." (PMID 34595242, 2021). "Results confirmed that inhibition of miR-378a-3p expression could significantly reduce the level of TNF-α, IL-1β, IL-6 in the serum of sepsis rats, and thus improved the inflammatory response induced by sepsis." (PMID 34565302, 2021). "In summary, we have demonstrated the PEGylated catalase can effectively regulate the production of cytokines by leukocytes, suppress the elevated level of AST, ALT, TNF-α, and IL-6 and mitigate the damage to the liver, kidney, lung function and other organs in mice with induced sepsis." (PMID 34888304, 2021).
Sepsis (continued). "Compared with APAP-treated PD-1–/– mice, APAP-treated WT mice had a higher fold change of C-reactive protein (CRP) and lactate levels and a cytokine profile that favored a proinflammatory imbalance, as indicated by increased sepsis severity markers such as IL-6 and a higher IL-6/IL-10 ratio." (PMID 33320839, 2021). "Some hypotheses suggest that sepsis is associated with an early overwhelming innate immune response, characterized by dysregulation of the overproduction of cytokines (TNF-α, IL-1β, IL-6, IL-8)." (PMID 34017259, 2021). "Furthermore, procalcitonin (an established biomarker for sepsis) and progranulin were significantly different, whereas interleukin-6 and C-reactive-protein were comparable between these two groups." (PMID 34956213, 2021). "It is likely that the dynamic cytokine (IL-6) dysregulation induces NETosis and coagulation in other non-COVID causes of sepsis." (PMID 34775962, 2021). "Given the important role of IL-6 in the inflammatory cascade, these preliminary findings suggest that Gal-3 may serve as an upstream mediator of the “cytokine storm” in sepsis and S-AKI." (PMID 33736691, 2021). "Baseline IL-6 levels in patients with SARS-CoV-2 infections were similar to those reported in patients with community acquired bacterial pneumonia but lower than in patients with sepsis or CRS induced by CAR T cell therapy." (PMID 33439360, 2021). "IL-6 regulates both the innate and adaptive immune response, is a well-consolidated marker of inflammation, such as systemic inflammation, sepsis, and autoimmune disease, and is also a prognostic marker for canine critical care patients with acute internal disease." (PMID 34564578, 2021). "Besides, the increase of IL‐6 in circulation can also greatly contribute to the onset and progression of sepsis." (PMID 33982381, 2021). "Additionally, down-regulation of lncRNA UCA1 and lncRNA HULC in LPS-induced sepsis mice and HMECs alleviated vascular injury associated with reduced ICAM1, VCAM1, and IL-6." (PMID 34055659, 2021). "In addition, the beneficial effects of monoclonal antibody-based anti-TNF-α, anti-IL-1β, or anti-IL-6 therapy individually on sepsis have previously been reported." (PMID 34065201, 2021). "This study found that GDF15 is positively correlated with IL-6 and IL-10, which may be due to the rapid increase of cytokines after the cytokine storm in sepsis." (PMID 34566964, 2021). "High levels of IL-6 correlate inversely with survival time in patients with sepsis." (PMID 34357984, 2021). "Second, to the best of our knowledge, our work firstly demonstrated the enhanced prognostic prediction value of NLR combined IL-6, which could guide the clinicians to adopt more appropriate and accurate management for sepsis patients." (PMID 33796105, 2021). "Some studied sepsis-biomarkers include complete blood picture, C-reactive protein, serum amyloid A, lipopolysaccharide-binding protein, Interleukin 6 (IL-6), Interleukin 8 (IL-8), Tumor Necrosis Factor alpha (TNFa), procalcitonin, and Cluster of Differentiation 163 (CD163)." (PMID 34452099, 2021). "If our limited kinetic could not illustrate this FRA-1 dependency for the IL-6 protein secretion in vitro, we observed in vivo that circulating IL-6 level were decreased in tolerant mice subjected to our sepsis model." (PMID 34712224, 2021). "Therefore, detecting the change of IL-6 concentration is of great significance for the early diagnosis of sepsis." (PMID 34281552, 2021). "Moreover, as already demonstrated by Witteveen and colleagues, elevated IL-6 at admission is one of the risk-predictor biomarkers for developing ICU-AW, independently from sepsis." (PMID 33755815, 2021). "Studies have shown that the pro-inflammatory cytokines (including TNFα, IL6, and macrophage inflammatory protein 2) secreted by inflammatory cells in sepsis-induced ALI can activate neutrophils and vascular endothelial cells to initiate and maintain pulmonary inflammation." (PMID 34584017, 2021).
Sepsis (continued). "Moreover, the strong prognostic value of IL-6 has been used to determine lethality in a polymicrobial sepsis model." (PMID 33946773, 2021). "In addition, it was observed that administration of tannic acid as an anti-inflammatory agent reduced the levels of inflammatory cytokines, TNF-α and IL-6, in sepsis as it was observed in bone marrow-derived macrophages cells." (PMID 35317115, 2021). "While IL-6 is sometimes used as a biomarker for cytokine storm activity in sepsis, the relationship between cytokine profiles and the risks associated with sepsis may be more complex." (PMID 33594340, 2021). "Moreover, plasma MCP-1 levels directly correlate with other cytokine levels (TNF-α, IL-6, IL-8, and IL-10) in the setting of sepsis." (PMID 33803628, 2021). "IL-6 was recognized as a marker of sepsis with high specificity." (PMID 34017259, 2021). "Furthermore, there are different studies highlighting a potential role for interleukin-6 (IL-6) in the diagnostic workup of AA: it seems that its use, in combination with serum lactate, could be useful in simultaneously establishing both the severity of sepsis and the prognosis of AA." (PMID 34530908, 2021). "SIRS, characterized by the release of huge amounts of pro-inflammatory cytokines, including tumor necrosis factor-α, interleukin-1β, interleukin-6, and interferon-γ named as “cytokine storm”, has been reported to be correlated with higher mortality in severe sepsis." (PMID 33967773, 2021). "For example, Stat3 inhibitor was shown reductions in inflammation and tumor development, which may prompt us to the application of a similar strategy against inflammatory diseases where IL6 is overproduced, such as sepsis and EAE." (PMID 35126382, 2021). "The results suggested IL-6 may be used as a prognostic biomarker for 28-day mortality in patients with sepsis, while the predictive accuracy of IL-6 is lower than that of NT-proBNP." (PMID 33446739, 2021). "Presepsin has a higher specificity for sepsis diagnosis compared with PCT and IL-6, and thus could be useful for the prognosis of sepsis and monitoring the course of the disease." (PMID 34118899, 2021). "Finally, the importance of the IL-6/IL-10 balance was stressed in predicting the sepsis outcome and mortality." (PMID 33500240, 2021). "In a study that collected serial samples from patients meeting sepsis-3 criteria until discharge, differences in cytokine measurements on Day 1 of sepsis were seen, where IL-1β, IL-10, IL-6, and IL-8 levels were among six cytokines found to be significantly elevated compared to controls." (PMID 33820537, 2021). "Sepsis-induced inflammation wasassessed by measuring interleukin-6 (IL-6), IL-10 and HMGB1 levels." (PMID 33605309, 2021). "In consistent with these results, we demonstrated that the recruitment of JMJD3 and NF-κB in the promoter regions of TNF-α, IL-1β, and IL-6 contributed to the upregulation of these pro-inflammatory cytokines via H3K27me3 demethylation, thus promoting inflammatory response in sepsis." (PMID 33413595, 2021). "Tumor necrosis factor-α (TNF-α), interleukin-1β (IL-1β), and IL-6 are three major inflammatory cytokines that actively participate in mediating the development of organ injury (e.g., that of the liver) induced by endotoxemia and sepsis." (PMID 34065201, 2021). "IL-6 levels were higher in three of the sepsis groups than in the control group." (PMID 34493028, 2021). "Indeed, LF was demonstrated to reduce interleukin 6 (IL6) and tumor necrosis factor-alpha (TNFα) in experimental settings simulating sepsis." (PMID 33498631, 2021). "IL-6 is an inflammatory cytokine and plays an important role in the early phase of sepsis." (PMID 34120605, 2021). "Inflammatory factors such as tumor necrosis factor-alpha (TNF-α), interleukin-6 (IL-6), and interleukin-1 (IL-1) act as key regulators of the immune response and play a critical role in the complex pathophysiological mechanisms of sepsis." (PMID 34867346, 2021).
Sepsis (continued). "Moreover, it has been documented that the plasma levels of TNF-α and IL-6 increased significantly in patients with sepsis and in animal models." (PMID 35003518, 2021). "Placental cytokine levels (TNF-α, IL-1β, IL-6) were also increased at 24 h after sepsis induction." (PMID 33632243, 2021). "As sepsis-induced disruption of tissue homeostasis leads to aberrant regulation of both anti- and pro-inflammatory cytokines (CKs), we sought to determine the expression of IL-1β, IL-6, IL-10, TGF-β1, and TNFα, the main drivers of tissue inflammation." (PMID 33803290, 2021). "The inability to distinguish MIS-C from sepsis using IL-6, CRP, and PCT could delay immunomodulatory treatment for MIS-C or inappropriate immunosuppression in sepsis." (PMID 34869111, 2021). "Additionally, CRP and IL-6 possess limited abilities to distinguish sepsis from other inflammatory conditions or to determine prognosis." (PMID 34055659, 2021). "Together, FUNDC1-dependent MAMs is important in LPS-induced sepsis and IL-6/STAT3 inhibitor might improve cardiac dysfunction through regulating the FUNDC1-dependent MAMs formation." (PMID 35118141, 2021). "In a mouse model of cecal ligation and puncture (CLP) sepsis, rGas6 treatment reduced lung serum levels of proinflammatory cytokines, such as IL-6 and IL-17, and mRNA levels of proinflammatory cytokines and chemokines, such as TNF-α, IL-1β, IL-6, IL-17, and MIP-2, at 20 h post-CLP." (PMID 34829903, 2021). "Oral administration of chemically stable MIC-1 (80 mg/kg) significantly reduced the expression of inflammatory markers (Tnf-α, Ifn-α, IL-1β, IL-6) in the liver, kidney, spleen, and colon and decreased spleen weight in the lipopolysaccharide (LPS)-induced sepsis / acute inflammation model in mice." (PMID 33793581, 2021). "We believe that by sequestering transcription factors that regulate expression of proinflammatory mediators, dnHMGA1 influenced the response of the MSCs during sepsis, as evidenced by decreased IL‐6 production in dnHMGA1 MSCs after exposure to PIS compared with WT MSCs." (PMID 33438259, 2021). "Excessive IL-6 production is a key feature of the condition known as “cytokine storm” and is considered to be a major contributor to vascular damage during disorders such as sepsis or systemic inflammatory response syndrome." (PMID 33668216, 2021). "The serum cytokines of sepsis are significantly increased, including IL-6, IL-1β, and TNF-α." (PMID 35118141, 2021). "Literature studies have investigated the role, both diagnostic and prognostic, of some biomarkers such as PCT, IL-6, IL-18, presepsin, etc., in patients with sepsis and septic shock without finding conclusive results." (PMID 34577843, 2021). "Monocytes from patients with sepsis had altered DNA methylation profiles compared to controls, with several hyper- and hypo-methylated CpG sites in monocytes from patients with sepsis correlating with increased constitutive production of IL-10 and IL-6." (PMID 33685492, 2021). "Beyond Day 1 of sepsis, both IL-6 and IL-8 remained significantly higher than controls." (PMID 33820537, 2021). "Authors have reported that serum IL-6 levels discriminated sepsis (AUC 0.83–0.94, p < 0.001; cut-off value, 52.6 pg/mL, 80.4% Se, 88.9% Sp) from controls, and also distinguished septic shock (AUC 0.71–0.89; cut-off value, 348.92 pg/mL, 76.1% Se, 78.4% Sp) from sepsis." (PMID 34460840, 2021). "In addition, sepsis increases the concentration of inflammatory factors (such as IL-6, TNF-α, HMGB1), which are the main inducers of apoptosis." (PMID 34057015, 2021). "Therefore, TNFα, IL-1β, and IL-6 are currently considered to be markers of the early phase of sepsis." (PMID 32793229, 2020). "Indeed, the intravenous infusion of riboflavin into the sepsis mice alleviated the plasma level of pro-inflammatory mediators, such as TNFα, IL-1β, IL-6, INFγ, MCP1, and NO5,6." (PMID 33154451, 2020). "The optimal cut-off level for IL-6 in neonates with culture proven sepsis was 313.5 pg/mL." (PMID 33233806, 2020).
Sepsis (continued). "Proinflammatory cytokines including IL-6 are universally elevated in sepsis and other infections." (PMID 33121497, 2020). "Among the proinflammatory cytokines, IL-6 is the most clinically suitable biomarker for sepsis." (PMID 32826331, 2020). "This is because a swift increase in the level of IL-6 was observed during the early phase (1–5 days) of sepsis in both the wild-type and S100A9 knock-out mice, and treatment with anti-IL-6 neutralizing antibodies was very efficient at decreasing the expansion of MDSCs in the early septic phase only." (PMID 32931721, 2020). "Indeed, the only cytokine commonly used in clinical practice for sepsis diagnostics is IL-6 in neonatology." (PMID 32948040, 2020). "Furthermore, the contents of TNF-α, IL-6, and IL-10 were detected in order to study the inflammation in mice with sepsis." (PMID 33376482, 2020). "TRPM7 expression and levels of TNF-α, IL-6 and IL-1β are increased in the serum of patients with sepsis diagnosis and those patients with sepsis and a high expression of TRPM7 have a decreased survival rate in comparison to patients with a low expression of TRPM7." (PMID 33291725, 2020). "According to this study findings, PCT, CRP, and IL-6 were shown to be highly significantly elevated in the confirmed sepsis cases when compared with the suspected cases, which proved not to be infected by both blood culture and PCR (p ≤ 0.001, p=0.001, p=0.004 respectively)." (PMID 33061986, 2020). "It has been shown that a low level of HDL-C negatively correlates with the severity of sepsis and is associated with a massive release of inflammatory mediators (i.e., tumor necrosis factor α (TNF-α), interleukin 1β (IL-1β), interleukin 6 (IL-6), and interleukin 8 (IL-8))." (PMID 33228032, 2020). "Furthermore, in spite of the documented efficacy of the IL-6 inhibitor tocilizumab in the treatment of COVID-195,6, IL-6 inhibitors may cause even more profound immunosuppression than steroids, increasing the risk of sepsis, bacterial pneumonia, gastrointestinal perforation, and hepatotoxicity." (PMID 32547788, 2020). "This indicates the accuracy of IL-6 to correctly discriminate sepsis cases from controls was good." (PMID 33233806, 2020). "Exposure of lipopolysaccharide (LPS)-activated human macrophages to acetylcholine resulted in a dose-dependent inhibition of such proinflammatory cytokines as tumor necrosis factor-α (TNF-α), interleukin 6 (IL-6), and IL-1β, involved in pathological processes of endotoxemia and sepsis." (PMID 32230846, 2020). "The optimal cut-off value of IL-6 among proven sepsis versus controls was 313.5 pg/mL." (PMID 33233806, 2020). "This contrasts with previous studies describing a failure to reduce IL-6 in GRdim mice because they were resistant to the anti-inflammatory effects of not only endogenous GCs in sepsis models but also of exogenous GCs treatment in the context of antigen-induced arthritis." (PMID 33679723, 2020). "Similarly, we found an increased TNF-α, IL-1β, and IL-6 levels in the serum, the hippocampus, and the frontal cortex at day 1 and day 10 after sepsis onset." (PMID 32457609, 2020). "We had previously investigated the diagnostic value of PTX3, IL6, and PCT individually in patients with sepsis or septic shock, where the results showed that each biomarker had good value in discriminating these patients from control patients who had no infections." (PMID 32481464, 2020). "In our previous study, we also indicated that eight functional polymorphisms (IL1B-1470, IL1B-511, IL1B-31, IL4-589, IL6-572, IL8-251, IL10-819, and TNFA-308) could be combined together to predict the risk of sepsis and organ dysfunction after trauma." (PMID 33281864, 2020). "Twenty-four hours after CLP, there were a significant increase in proinflammatory cytokines (TNF-α, IL-1β, and IL-6) in serum and an elevated death rate in rats, while the surviving rats developed septic syndrome; this demonstrated that our sepsis model was successfully established." (PMID 32765805, 2020).